CTLA4 (cytotoxic T-lymphocyte associated protein 4)
Diseases named in the same sentence as CTLA4 in open-access papers (continued):
Sharing a sentence is not in itself a finding about the gene and the disease.
tumor (continued). "ADC‐159 was combined with anti‐PD‐L1, anti‐PD‐1 or anti‐CTLA‐4 antibodies and used to treat immune‐competent mice bearing CT‐26 allograft tumours." (PMID 38602256, 2024). "Targeted therapies such as PD-1 inhibitors and CTLA-4 inhibitors can block these checkpoints, restore the anti-tumor activity of T cells, and enhance the immune system’s capacity to recognize and attack tumors." (PMID 39234260, 2024). "The combination of CTLA-4 and PD-1 inhibitors can enhance the activation of tumor-specific T cells and facilitate the conversion of a tumor microenvironment from ‘‘cold’’ to ‘‘hot’’." (PMID 39001412, 2024). "Since the approval of the first immune checkpoint inhibitor (ICI), ipilimumab (anti-CTLA-4), in 2011, additional ICIs have emerged as a significant therapeutic approach to reinvigorate anti-tumor responses and eliminate malignant cells." (PMID 38785789, 2024). "ICIs regulate CD8-positive T lymphocytes and regulatory T (Treg) cells by targeting the PD-1, PD-L1 and CTLA-4 pathways, thereby restoring the body’s tumor-suppressed immune function and enabling the body to produce an efficient immune response to tumor cells." (PMID 38348049, 2024). "Patients with pT1-T2 tumours had significantly lower levels of CTLA-4 on CD4 cells when compared to patients with pT3-T4 lesions (adjusted p= 0.0181)." (PMID 39474426, 2024). "Linsitinib alone had a modest inhibitory effect on tumor growth, and the combined treatment of linsitinib with anti–CTLA-4 more effectively impeded tumor growth and extended survival." (PMID 39545420, 2024). "In this study, we demonstrate that the combination of RASG12C(ON) and SHP2 inhibition also sensitises immune evasive tumours to anti-CTLA-4 treatment, leading to durable responses." (PMID 39322643, 2024). "Therapies targeting the PD-1/PDL-1 and CTLA-4 checkpoints were pioneers in human medicine, and a few studies have investigated a similar therapeutic approach in canine tumours." (PMID 38893123, 2024). "Another study showed a different outcome, the elevated density of CD4+ or CD8+ TILs in patients with high CTLA-4 expression on interstitial lymphocytes or tumor cells, the superior outcomes in the group of high CTLA-4 expression level." (PMID 39845973, 2024). "LGALS3 expression showed a significant positive association with CD274, TIGIT, PDCD1, HAVCR2, CTLA4, LAG3, as well as PDCD1LG2 after adjustment for tumor purity in HCC." (PMID 38643145, 2024). "By preventing CTLA-4 from delivering its inhibitory signals, these inhibitors effectively unleash the immune system, allowing T cells to attack tumor cells more vigorously." (PMID 39335671, 2024). "Immune checkpoint inhibitors such as anti-PD-1/PD-L1 and anti-CTLA-4 antagonists, which function by activating the adaptive immune system against tumor cells, have revolutionized cancer therapy." (PMID 39482534, 2024). "When assessed by Q‐PCR, we also observed a 4.56‐fold increase in CTLA‐4 levels compared to vehicle treated tumours." (PMID 38602256, 2024). "We examined the ability of these 5 anti-CTLA-4 compounds to stimulate interferon-γ (IFN-γ) production in mouse tumor-infiltrating lymphocytes (TILs)." (PMID 38312352, 2024). "Among them, the interaction of programmed death receptor 1 (PD-1) with programmed cell death ligand-1 (PD-L1), cytotoxic T-lymphocyte-associated protein-4 (CTLA-4) and CD80/86 is the main mechanism of tumour cell escape." (PMID 39391313, 2024). "Although both anti-CTLA-4 and anti-PD-1 therapies can block the signaling pathways that inhibit T cell-mediated tumor killing, acting as a type of “release the brakes” mechanism for anti-tumor effects, their mechanisms of action differ." (PMID 38672120, 2024). "Remarkably, cadonilimab displays higher binding avidity in a high-density PD-1 and CTLA-4 setting, offering potential advantages in tumor-like environments." (PMID 38475778, 2024).
tumor (continued). "Nonetheless, using an antibody to suppress CTLA-4 can strengthen and prolong T-cell activation in cancer treatment, boosting the immune response against tumor cells." (PMID 39273605, 2024). "Combination therapy with recombinant IL-15 and blocking antibodies against CTLA-4 has been shown to increase survival and reduce tumor growth in murine tumor models, as compared to one of the treatments alone." (PMID 39204319, 2024). "Next, we calculated the IPS in the POSTN‐high and POSTN‐low expression groups to determine the tumor immunogenicity for predicting response to immune checkpoint inhibitor (ICI) therapy such as CTLA‐4 and PD‐1/PDL1 inhibitors." (PMID 38389400, 2024). "Meanwhile, the CTLA4 level in the single-cell suspension obtained from the tumor tissue was ground and filtered, and it was detected with immunoblots." (PMID 38398223, 2024). "The investigation into the effects of CTLA-4 on T cells binding tumor cells holds significant importance due to the pivotal role of CTLA-4 in regulating immune responses." (PMID 38473398, 2024). "CTLA-4 expression in lymphocytes is thought to be driven by lung cancer or the tumor microenvironment." (PMID 38226621, 2024). "When CTLA4-mediated interactions with squamous cell carcinoma cells were blocked in vitro, tumor-CD80 engaged instead with CD28 on activated T cells." (PMID 39575257, 2024). "The IHC results revealed that CTLA4 was upregulated in the tumor tissues compared to the controls, but the levels of PD-1 and PD-L1 were not significantly different." (PMID 38398223, 2024). "This approval highlights LAG-3’s potential as a promising tumor immunotherapy target, succeeding PD-1 and CTLA-4." (PMID 38928150, 2024). "CAR-T cells with CTLA4 blockade exhibited higher proliferative capacity and better anti-tumor efficacy compared to CAR-T cells with PD-1 blockade." (PMID 38571495, 2024). "The data showed that combining RX-5902 with CTLA-4 or PD-1 antagonists led to a reduction in tumor growth in four T1 and human immune systems and MDA-MB-231 xenograft models." (PMID 38893132, 2024). "We gain insight into the expression and function of specific CTLA-4 related lncRNAs, evaluating their impact on immune regulation and tumor progression and putting forward some potential drugs." (PMID 39143529, 2024). "Our findings demonstrated that the combination of activated CD8+ T cells with doxorubicin/anti-CTLA-4 Nb co-loaded liposomes can effectively eradicate tumor cells both in vivo and in vitro." (PMID 38824143, 2024). "These inhibitors function by preventing the interaction between CTLA-4 and its ligands (B7-1 and B7-2), thereby eliminating the inhibitory signals on T cells, leading to enhanced anti-tumor immune responses." (PMID 39234260, 2024). "The authors reported a significant increase of CD8 + T cells and NK cells in the brain of GBM tumor-bearing mice and increased survival times if combinations of anti-CTLA-4 and anti-PD1 conjugates were used." (PMID 37587290, 2024). "The FDA has approved the two human mAbs Ipilimumab and Tremelimumab, which bind to CTLA-4 specifically, thereby blocking their interaction with B7.1 and B7.2, leading to antitumor immune response induction against various types of tumor cells." (PMID 38255322, 2024). "The combination of PD1 and CTLA4 blockers in cancer treatment has been suggested to augment the activation of anti-tumor immune response to improve outcomes in patients." (PMID 39416390, 2024). "Although the process of T-cell exhaustion can hinder anti-tumor immunity, this dysfunctional state can be reversed by targeting programmed cell death protein 1 (PD-1) and CTLA-4, thereby enhancing tumor immunity." (PMID 39146202, 2024). "The results of our investigation demonstrate a significant synergistic effect between tumor-specific T cells and anti-CTLA-4 Nb/DOX co-loaded liposomes." (PMID 38824143, 2024). "While 16 Gy + anti-CTLA4 yielded an overall tumor growth delay, only a cohort of mice were fully cured." (PMID 39199612, 2024).
tumor (continued). "For example, only the combined use of focal radiation therapy and CTLA-4 inhibition therapy did induce activation of systemic anti-tumor T-cells in metastatic NSCLC, whereas the latter therapy alone was largely ineffective." (PMID 39727496, 2024). "BsAbs maintain efficacy while potentially improving safety through mechanisms such as reduced CTLA4 activity and specifically targeting the tumor microenvironment." (PMID 38713378, 2024). "In this study, it was observed that targeting CD47 led to an upregulation of CTLA4 levels in tumor cells, as evidenced by the IHC and IF assays." (PMID 38398223, 2024). "Accordingly, tumor growth was drastically suppressed in mice treated with a combination of anti-CTLA-4 and TPPU compared to mice treated with vehicle, anti-CTLA-4, or TPPU alone." (PMID 38330013, 2024). "Western blot analyses of the tumors showed up‐regulations of PD‐L1, STAT1, p‐STAT1, and IRF‐1 expression in a single small tumor from APG‐157 + anti‐CTLA‐4 treated group." (PMID 38686626, 2024). "In our experience, IMAEs in patients receiving an additional CTLA-4 inhibitor with CIT can be managed by the tumor board, and this can prolong the benefits achieved with IO." (PMID 39703851, 2024). "To evaluate mHAdLyp.sT’s effects on 4T1 tumor growth and metastasis we compare it with ICIs (anti-PD-1 and anti-CTLA-4 antibodies) and assess if it can synergize with ICIs to inhibit tumor growth and metastasis." (PMID 38267626, 2024). "Antibody blocking of cytotoxic T-lymphocyte antigen-4 (CTLA-4) or programmed death-1 (PD-1) reduces the inhibition of anti-tumor cytotoxic T-cell responses resulting from the release of negative regulators of immune activation called immune checkpoints (IC)." (PMID 38613802, 2024). "Inhibitory immune checkpoint molecules, such as PD-1, PD-L1, and CTLA-4, are frequently expressed within the tumor microenvironment and can dampen immune responses against cancer cells." (PMID 38378721, 2024). "CTLA-4 blockers can lift the restrictions CTLA-4 places on T cell signaling, allowing antitumor lymphocytes to continue their effector responses against tumor cells." (PMID 38384806, 2024). "In this tumor model, concurrent treatment with anti-CTLA4 and dietary ω-3 PUFAs supplementation resulted in an approximately 35% inhibition of tumor growth in mice, compared to treatment with anti-CTLA4 and the control diet." (PMID 38330013, 2024). "Tumor growth analysis showed that APG‐157 combined with the anti‐CTLA‐4 antibody suppressed tumor growth." (PMID 38686626, 2024). "In conclusion, TCM has the potential to boost the effectiveness of CTLA-4 inhibitors through multi-link immune regulation while also playing a larger role in tumor immune control." (PMID 39660124, 2024). "Clinical studies of anti-CTLA4 monoclonal antibodies along with tumor peptide vaccines also have proven that using CTLA-4 monotherapy before vaccination strengthens the antitumor reaction, enhancing therapeutic results." (PMID 38500876, 2024). "The only significant difference was observed for expression of CTLA-4 on CD4 cells in relation to the size of the tumour." (PMID 39474426, 2024). "Upregulation of immune checkpoints, such as CTLA-4, by regulatory T cells, Tregs, or PD-1/PD-L1 axis in the tumor microenvironment results in abrogation of effector T-cell function that compromises immune clearance of tumor clones." (PMID 39470352, 2024). "ICIs such as PD-1, PDL-1, and CTLA-4 antibodies can restore anti-tumor immune response by antagonizing T cell activation inhibitory molecules and promoting T cell recognition of tumors." (PMID 38656878, 2024). "Initially, we assessed the effect of anti-PD-1 and/or anti-CTLA-4 on subcutaneous 3LL-ΔNRAS tumours in immunocompetent mice." (PMID 39322643, 2024). "This blockade of the CTLA-4 and PD-1 signaling pathways can synergistically enhance the anti-tumor immune responses in patients, thereby improving their immune response rates." (PMID 38627681, 2024).
tumor (continued). "Anti-CTLA-4 and anti-PD1/PDL1 are the most commonly used ICB biologics in clinical tumor immunotherapy, but they are also associated with significant toxicities and side effects." (PMID 39456702, 2024). "Mechanistic insights into the role of anti-CTLA-4 and anti-PD-1-induced anti-tumor immunity have emerged." (PMID 39247203, 2024). "ICIs enhance anti-tumor immune responses by blocking immune checkpoint proteins that inhibit T cell function, such as cytotoxic T lymphocyte antigen 4 (CTLA-4) and programmed death protein 1 (PD-1)." (PMID 39660130, 2024). "CD80 is shown to engage with the T cell inhibitory molecule CTLA4, leading to immune suppression and the promotion of tumor growth." (PMID 38891044, 2024). "Researchers have found that in preclinical models of solid tumors such as breast and colorectal cancer, the combination of an anti-A2AR antibody (CPI-444) with an anti-PD-1 or anti-CTLA-4 antibody inhibits tumor growth and is more effective than monotherapy." (PMID 39329710, 2024). "Blocking CTLA-4 reduces the infiltration of MDSCs in the tumor microenvironment (TME), diminishing their immunosuppressive effects and potentially enhancing the efficacy of PD-1/PD-L1 inhibitors in tumor suppression." (PMID 39839672, 2024). "The appearance of a morbilliform (maculopapular) rash on the trunk and extremities was noted in tumor patients following treatment with either anti-CTLA-4, PD-1 or PD-L1 therapy." (PMID 39795946, 2024). "Since CTLA-4-mediated inhibition is crucial for T cell activity, immunomodulation via blockade of this pathway is a promising approach to prevent inactivation of tumor-reactive T cells." (PMID 38340727, 2024). "The response to anti-checkpoint blockade therapy can be influenced by tumor-infiltrating immune cells, and upregulation of some immunological checkpoint genes, such as PD-1 and CTLA-4, can be due to tumor-infiltrating CD4+ T cells." (PMID 38356712, 2024). "Blocking CTLA-4 can boost the body’s immune response against tumor cells, restoring T-cell activity and extending memory T-cell survival." (PMID 39080807, 2024). "While neoAg SLP vax or ICT led to robust rejection of Y1.7LI when initiated on day 7 post-transplant, a majority of mice displayed tumor outgrowth when treatment with anti-CTLA-4, anti-PD-1, or neoAg SLP vax was initiated on day 12 post-transplant." (PMID 39446585, 2024). "CTLA4apt-STAT3, a CTLA4 aptamer that delivers STAT3 siRNA to tumor cells, CD8+ T cells and Treg cells, finally inducing activation of the antitumor immunity." (PMID 38245798, 2024). "CpG combined with low-dose anti-OX40/CTLA-4 triple immunotherapy can eliminate Tregs in a tumor and has a curative effect on central nervous system lymphoma in mice." (PMID 38807592, 2024). "Preclinical data have shown that SLC-0111, a CAIX inhibitor, acts synergistically with immune checkpoint inhibitors such as anti-PD1 or anti-CTLA4 to suppress tumor vascularization and metastasis in a TNBC xenograft model." (PMID 38715072, 2024). "Co-inhibition with other immune checkpoints such as CTLA-4 or modification of the tumor microenvironment through anti-angiogenic agents can enhance the immune response." (PMID 39014460, 2024). "In the CT26 and WEHI-164 syngeneic models, high frequency of complete regression (CR) of tumor was observed in anti-CTLA4 and TU2218 combination group, showing 60% (6/10), and 80% (8/10) of CR, respectively." (PMID 39105882, 2024). "Since the FDA approved immune checkpoint inhibitors (ICIs) targeting CTLA4 and PD-1 for melanoma treatment, ICIs have revolutionised tumour therapy." (PMID 38660136, 2024). "High expression levels of FAM202B correlated with increased resistance to sunitinib and enhanced responsiveness to immunotherapy, as evidenced by associations with tumour mutation burden, PDCD1, CTLA4 and TIDE scores." (PMID 39198940, 2024).
tumor (continued). "When IL-15 anti–programmed cell death ligand 1 (PD-L1) and anti–cytotoxic T-lymphocyte antigen 4 (CTLA-4) antibodies were used together in mouse tumor models, the latter were able to survive for a longer time." (PMID 39507777, 2024). "Cyanine5 (Cy5)-labeled H11 binds to CTLA-4 on Tregs extracted from both tumor and spleen, with intratumoral Tregs showing higher CTLA-4 expression than those from the spleen." (PMID 39149504, 2024). "Cancer vaccines are an appealing anti-CTLA-4 therapeutic strategy because they enhance immunogenic response and tumor specificity by targeting neoantigens." (PMID 38956700, 2024). "Anti-CTLA-4 monoclonal antibodies (mAb) further induce potent anti-tumor effects by depleting CTLA-4-expressing Treg cells within the tumor microenvironment (TME) through Ab-dependent cytotoxic activity (ADCC)." (PMID 38473398, 2024). "On the basis of these findings, metformin was combined with anti-CTLA4 therapy in a 4T1 breast tumor model, and this approach resulted in significant improvements in tumor burden, survival rate, and CTL activity." (PMID 39080767, 2024). "According to the statistical results, the proportions of FGFBP2+ NK cells, IL1RL1+ T cells, CTLA4+ T cells, Myeloid cells 1, and Plasma B cells were higher than that of normal in tumor tissues." (PMID 38604154, 2024). "Immune checkpoint inhibitors(ICIs) targeted CTLA-4 and PD-1 have been demonstrated to prompt tumor cell death by immunogenic cell death." (PMID 38443363, 2024). "Mechanistic analyses suggest that mIL12 remodels the tumor microenvironment into a pro-inflammatory state and upregulates the expression of PD-1 and CTLA-4." (PMID 39584994, 2024). "Notable co-stimulatory markers on lung DCs are PD-L1 and CTLA-4, whose expression has tumor-promoting effects due to the lowering of immune cell infiltration." (PMID 39481389, 2024). "DC vaccines developed using CD133 mRNA and MUC1 mRNA along with CTLA4 blockade have shown enhanced immune response and inhibition of tumor growth using in vivo murine TNBC models." (PMID 38715072, 2024). "Blocking the PD‐L1 and PD‐1 interaction with immune checkpoint inhibitors, such as anti‐PD‐1 and CTLA‐4, allows T cells to recognize and effectively eliminate tumour cells." (PMID 38693853, 2024). "PD-1 inhibitors function in the tumor setting, while CTLA-4 inhibitors act on lymphoid tissue, resulting in a wide and different set of adverse events." (PMID 38410760, 2024). "Anti-CTLA-4 can expand the number of T cells in lymphoid organs and tumor tissues, while anti-PD-1 can overcome the inhibition of effector T cells." (PMID 38809459, 2024). "Data from 274 hepatitis B virus positive tumor patients who received PD-1 or/and CTLA4 inhibitor treatment and had immune cell detection results were collected from Henan Cancer Hospital for retrospective analysis." (PMID 39931579, 2024). "In the context of HCC, CTLA-4 exerts its suppressive effects by curtailing the activity of tumor-infiltrating lymphocytes, thereby facilitating tumor immune evasion and contributing to the progression of the malignancy." (PMID 39502703, 2024). "cDC1 reprogramming synergized with anti-PD-1 or anti-CTLA-4 treatment leading to increased CR in B16 and B2905, which also resulted in expansion of tumor antigen-specific IFNγ+CD8+ and IFNγ+CD4+ T cells in peripheral blood." (PMID 39236156, 2024). "While PD-1 suppresses anti-tumor T cell responses later on, CTLA-4 prevents early T cell activation." (PMID 39731596, 2024). "In recent years, the development of immunotherapy represented by PD‐1 and CTLA‐4 blockade has fundamentally changed the tumour treatment paradigm." (PMID 38279870, 2024). "First, immune checkpoints such as PD-1 and CTLA-4 interact to form a complex immune suppression network, making their anti-tumor mechanisms more difficult to predict and understand." (PMID 39743998, 2024).